CKB (creatine kinase B)
Diseases named in the same sentence as CKB in open-access papers (continued):
Sharing a sentence is not in itself a finding about the gene and the disease.
breast carcinoma (3 papers, 2021 to 2025). "Higher CKB mRNA or protein levels were also found to be prognostic of reduced relapse-free survival (RFS) across all molecular subtypes of breast cancer." (PMID 35008190, 2021). "Although limited breast cancer cases were available to query at the protein level, high levels of CKB were also significantly correlated with reduced overall survival (OS)." (PMID 35008190, 2021). "The Cancer Genome Atlas (TCGA) database was queried to compare normalized CKB mRNA expression in breast cancer patients." (PMID 35008190, 2021). "First, we compared CKB expression levels in a panel of breast cancer cell lines representing various molecular subtypes." (PMID 35008190, 2021). "CKB is a creatine kinase brain isoform that promotes invasion and metastasis of breast cancer." (PMID 36142451, 2022). "In other breast cancer cell types that regulate CKB in a hypoxia-dependent manner, such as MCF-7 cells, increased CKB expression may be necessary to supplement energy production when oxygen is limited and glycolysis is the predominant pathway to generate ATP." (PMID 35008190, 2021). "In contrast, in ER+ MCF-7 breast cancer cells, CKB mRNA levels increased in response to hypoxia." (PMID 35008190, 2021). "Therefore, HIF-1 directly regulates CKB expression in breast cancer cells, as reported for the colon." (PMID 35008190, 2021). "In proteomic screens of prostate, lung, and HER2+ breast cancers, CKB was elevated." (PMID 35008190, 2021). "CKB is expressed in all subtypes, with enrichment in patients with HER2+ breast cancer relative to basal-like or luminal A subtypes." (PMID 35008190, 2021). "Based on CKB’s well-described role in regulating energy metabolism, and prior studies using creatine analogs to inhibit the creatine kinase pathway, including cyclocreatine (cCr), we sought to determine whether CKB plays a key role in mediating breast cancer metastasis." (PMID 35008190, 2021). "Creatine kinase brain isoform (CKB) was identified as a highly differentially expressed gene in a screen of HIF-1 wild type and knockout mammary tumor cells derived from a transgenic model of metastatic breast cancer." (PMID 35008190, 2021).
prostate carcinoma (3 papers, 2021 to 2025). A carcinoma that arises from epithelial cells of the prostate gland. "Overall, our study indicates that CKB downregulation is associated with poor prognosis in prostate cancer, and CKB downregulation functionally promotes prostate cancer progression, at least in part by promoting AKT activation and EMT." (PMID 34706306, 2021). "Moreover, a lower CKB mRNA level is significantly associated with worse prognosis in prostate cancer patients, such as higher tumor stage and grade and future relapse." (PMID 34706306, 2021). "In summary, cancer genomics and proteomics data clearly indicate that CKB mRNA and protein expression are significantly downregulated in multiple solid cancer types, which is associated with poor prognosis and shorter survival, including in prostate cancer." (PMID 34706306, 2021). "However, public RNA-seq datasets indicate that CKB is downregulated in human solid tumors, and its lower expression is associated with a worse prognosis in cervical, head–neck, colon, gastric, kidney, ovarian, pancreatic and sarcoma prostate cancer patients." (PMID 35664305, 2022). "All these results indicate that CKB downregulation activates AKT in prostate cancer cell models and patient samples." (PMID 34706306, 2021). "CKB mRNA is consistently downregulated in human prostate cancers compared to normal protein tissues across multiple well-cited datasets." (PMID 34706306, 2021). "AKT activation is one of the most prominent signaling events upon CKB silencing in prostate cancer cells, which is in line with prostate cancer TCGA data." (PMID 34706306, 2021). "To investigate the mechanism and downstream signaling pathways of CKB in prostate cancer cells, we performed a focused proteomics study using a Human Phospho-Kinase Array." (PMID 34706306, 2021). "For a detailed study on CKB, we chose to focus on prostate cancer, one of the cancer types of our interest." (PMID 34706306, 2021). "We have also demonstrated that CKB downregulation is a poor prognosticator, which is sufficient to promote prostate cancer progression." (PMID 34706306, 2021). "We found that CKB protein levels are significantly lower in prostate cancers (n = 141) than in normal prostate tissues (n = 115) (Chi-Square=21.5, P < 1.0E-5)." (PMID 34706306, 2021). "Mechanistically, we found that inhibiting AKT activation is a critical part of CKB's mechanism of action in prostate cancer progression." (PMID 34706306, 2021). "In our study, we set out to investigate the role of CKB in prostate cancer progression and its mechanism of action." (PMID 34706306, 2021). "Similarly, silencing CKB in 2 other prostate cancer cell lines DU145 and VCaP reduces E-cadherin and induces Vimentin." (PMID 34706306, 2021). "This further supports that low expression of CKB is a poor prognosticator in prostate cancer." (PMID 34706306, 2021). "As AKT activation is crucial for many cancer types, CKB downregulation, as seen in multiple epithelial cancer types, may be an integral part of general mechanisms underlying AKT activation beyond prostate cancer, which warrants further investigation." (PMID 34706306, 2021). "Of note, CKB inhibits EMT and prostate cancer progression by sequestrating AKT's interaction with and activation by mTORC2 complex." (PMID 34706306, 2021). "Given the crucial role of AKT signaling in survival and proliferation of prostate cancer cells, we next set out to test if the 84aa CKB fragment inhibits EMT, survival and proliferation of prostate cancer cells." (PMID 34706306, 2021). "To recapitulate CKB downregulation as observed in patient tumors, we next investigated the impact of CKB silencing on EMT and prostate cancer progression." (PMID 34706306, 2021). "In summary, we have uncovered that brain-subtype creatine kinase (CKB) is a crucial suppressor of EMT and prostate cancer progression through inhibiting AKT activation." (PMID 34706306, 2021).
prostate carcinoma (continued). "By characterizing EMT marker expression and cellular phenotypes, we have validated that CKB overexpression inhibits, while its silencing promotes EMT and prostate cancer growth." (PMID 34706306, 2021). "Phenotypically, CKB overexpression suppresses, while its silencing promotes, EMT and cell migration, xenograft tumor growth and metastasis of prostate cancer cells." (PMID 34706306, 2021). "We found that CKB downregulation promotes AKT activation, EMT and prostate cancer progression." (PMID 34706306, 2021). "Examining 352 TCGA prostate cancer patient samples that have both RNA-seq mRNA and RPPA proteomics data, we found that p-S473-AKT level is higher (P = 0.0032) in 36% of patient samples that have lower levels of CKB expression (Z score <-0.5)." (PMID 34706306, 2021).
schizophrenia (3 papers, 2024 to 2025). A major psychotic disorder characterized by abnormalities in the perception or expression of reality. "Regarding intelligence and schizophrenia, MAAT identified 21 genes with high association levels in these two traits, where the significant function of ACTR1A, C22orf46, CKB, CYP2D6, LRRC37A, NCK1, and ZMAT2 have been well validated in large-scale GWAS studies." (PMID 39905509, 2025). "Interestingly, a low expression level of CKB was found in postmortem brain samples from people with schizophrenia." (PMID 40051599, 2024).
depression (2 papers, 2021 to 2022). "Mirroring our CKB results, creatine studies have also found sex-specific signals in the context of depression." (PMID 33414381, 2021). "In support of past studies, our findings warrant further investigation of CKB activity and creatine concentrations in the context of depression." (PMID 33414381, 2021). "As for the relationship of depression with CVD, our result (HR = 1.40, 95% CI, 1.09–1.81) was similar with CKB (HR = 1.33, 95% CI, 1.15–1.53) and CHARLS study (HR = 1.39, 95% CI, 1.22–1.58)." (PMID 36501202, 2022).
gastric cancer (2 papers, 2015 to 2021). A primary or metastatic malignant neoplasm involving the stomach. "We found that reduced SRC and LYN methylation and increased CKB methylation was associated with gastric cancer." (PMID 26460485, 2015). "In this study, we aimed to evaluate SRC, LYN and CKB protein and mRNA expression, as well as their promoter methylation, in gastric cancer." (PMID 26460485, 2015). "Expression of SRC, LYN and CKB in gastric cancer is significantly associated with tumor invasion and lymph node and distant metastases, as well as with MYC expression, which is also a possible biomarker for GC." (PMID 26460485, 2015).
Hearing impairment (2 papers, 2018 to 2024). A decreased magnitude of the sensory perception of sound. "In HD, reduced expression and activity of CKB is associated with motor deficits and hearing impairment." (PMID 30518638, 2018). "Enhancing CKB activity by creatine supplements ameliorated the motor deficits and hearing impairment of HD mice." (PMID 30518638, 2018).
Hypoglycemia (2 papers, 2020 to 2023). A decreased concentration of glucose in the blood. "CKB knockdown also caused tumor cell cycle arrest in the G2 phase, resulting in inactivation of Akt and increased apoptosis of Skov3 cells, and more significant effects were observed under hypoxia and hypoglycemia conditions." (PMID 33281799, 2020).
liver cancer (2 papers, 2024 to 2026). An epithelial or non-epithelial malignant neoplasm that arises from the liver. "Using genetic instruments identified in CKB, we found genetic predisposition to accelerated liver aging was associated with higher risks of cirrhosis and liver cancer (HR = 3.94 [3.20-4.86] and 7.82 [2.05-29.80]), further validated in Biobank Japan." (PMID 42218728, 2026).
lung carcinoma (2 papers, 2004 to 2025). "Here, we demonstrate that CKB is essential for CK enzymatic activity in several cancer cell lines, including non–small cell lung cancer (H1299), osteosarcoma (143B), and ovarian adenocarcinoma (OVCAR8)." (PMID 41072771, 2025). "In summary, our study identifies CKB as a regulator of NSCLC metastasis, supporting the rationale for pursuing CK-targeted strategies for combating lung cancer progression." (PMID 41072771, 2025). "We show that CKB is required for non–small cell lung cancer (NSCLC) metastasis to the lung and liver in vivo, not by altering migration or chemotaxis, but rather by promoting resistance to detachment-induced cell death (anoikis)." (PMID 41072771, 2025).
lung squamous cell cancer (2 papers, 2014 to 2023). "Three proteins, GSTP1, heat shock protein beta-1 (HSP27), and creatine kinase brain-type (CKB), were validated using Western blot and immunohistochemistry, and the authors proposed them as potential biomarkers for early detection of lung squamous cell carcinoma." (PMID 24550697, 2014).
oligospermia (2 papers, 2016 to 2023). Decreased number of spermatozoa in the semen. "The CKB gene encodes an enzyme creatine kinase, and the elevated level of creatine kinase in the sperm causes oligospermia and male sterility." (PMID 37229195, 2023). "Gene CKB encodes the enzyme creatine kinase, and previous studies have reported that elevated levels of creatine kinase in the sperm are associated with severe oligospermia and male infertility." (PMID 27842509, 2016).
osteosarcoma (2 papers, 2025). A usually aggressive malignant bone-forming mesenchymal neoplasm, predominantly affecting adolescents and young adults. "We also extend our analysis to other metastatic cell lines, such as OVCAR8 (high-grade serous ovarian cancer) and 143B (osteosarcoma), both of which we show rely on CKB for CK activity, making them susceptible to CK-targeting therapies." (PMID 41072771, 2025).
astrocytoma (1 paper, 2021). "Brain- and muscle-type CK isoforms were described in glial (astrocytes and Bergmann glia) and Purkinje neurons, respectively, of normal human brain and a shift from CKB to increased M-isoform expression has been reported in high grade astrocytoma and GBM." (PMID 34502484, 2021).
bipolar disorder (1 paper, 2012). A disorder of the brain that causes unusual shifts in mood, energy, activity levels and the ability to carry out day-to-day tasks. "The decreased output of ATP may lead to further consequences such as a reduction in CKB involved in the storage of high-energy phosphates as observed in our dataset and bipolar disorder with mitochondrial dysfunction." (PMID 22558445, 2012).
cervical cancer (1 paper, 2005). A primary or metastatic malignant neoplasm involving the cervix. "This argument is also supported by an observation that activity of creatine kinase B, a ROS sensitive protein, is downregulated in cervical cancer." (PMID 15801986, 2005).
cervical squamous cell carcinoma (1 paper, 2022). A squamous cell carcinoma arising from the cervical epithelium. "The expression of CKB varies among TCGA tumors and is associated with a good prognosis of cervical squamous cell carcinoma, endocervical adenocarcinoma, and kidney chromophobe." (PMID 35664305, 2022).
colitis (1 paper, 2021). Inflammation of the colon. "In colitis mouse models induced by dextran sulfate sodium or 2,4,6-trinitrobenzene sulfonic acid, expression of CKB is reduced, and intestinal epithelial integrity is compromised with increased intestinal permeability." (PMID 34706306, 2021).
endometrial cancer (1 paper, 2022). Primary or metastatic malignant neoplasm involving the endometrium (mucous membrane that lines the endometrial cavity). "CKB had lower expression in endometrial cancer samples vs. normal tissue based on a CPTAC database of all races." (PMID 35887124, 2022).
esophageal cancer (1 paper, 2021). A primary or metastatic malignant neoplasm involving the esophagus. "Our analysis showed that following five genes were most significantly downregulated in esophageal cancer: C16orf89 (9.78E−08), AR (1.01E−07), CKB (1.17E−07), ADH1B (1.79E−07), and NCAM1 (2.15E−07)." (PMID 33828156, 2021). "With respect to downregulated genes, C16orf89, AR, CKB, ADH1B, and NCAM1 were the leading downregulated genes in patients with esophageal cancer." (PMID 33828156, 2021).
Fanconi anemia (1 paper, 2025). Fanconi anemia (FA) is a hereditary DNA repair disorder characterized by progressive pancytopenia with bone marrow failure, variable congenital malformations and predisposition to develop hematological or solid tumors. "First, GSEA revealed that CKB was enriched in the Fanconi anemia pathway, Wnt signaling pathway, and FoxO signaling pathway." (PMID 40600620, 2025).
Infertility (1 paper, 2021). "Of interest, some candidates related to sperm and infertility were identified, containing MORC1, TDRD9, ZFYVE21, ADGRB3, SPAG17, CKB, and WDR3, which may have effects on sperm motility and fertilization." (PMID 33477586, 2021).
inflammatory bowel disease (1 paper, 2021). A spectrum of small and large bowel inflammatory diseases of unknown etiology. "Concordantly, in inflammatory bowel disease patient tissues, CKB expression is significantly downregulated as compared to tissues from healthy control individuals." (PMID 34706306, 2021).
ischemic stroke (1 paper, 2018). A stroke disorder caused by obstruction of blood flow to the brain, due to thrombotic (local blood clot formation) or embolic (due to a blood clot or other material traveling from another site) event. "Notably, circulating levels of CKB and CMPK were higher in ischemic strokes than controls (p = 0.050 and p = 0.047, respectively)." (PMID 29784938, 2018).
leukemia (1 paper, 2024). A malignant (clonal) hematologic disorder, involving hematopoietic stem cells and characterized by the presence of primitive or atypical myeloid or lymphoid cells in the bone marrow and the blood. "The role of CKB or GATM in the mediation of TATA‐induced anti‐leukemia effects warrants future study." (PMID 39049685, 2024).
liposarcoma (1 paper, 2007). A usually painless malignant tumor that arises from adipose tissue. "Genes highly expressed in the dedifferentiated/pleomorphic liposarcomas included cell-cycle genes like CCNA2, CCNB2, CDC2, KIFC1, KIF23 and PTTG1, motility genes like AMFR, ANXA1, CKB, CNN2 and FN1 and homeostasis-related genes." (PMID 17359542, 2007).
macular degeneration (1 paper, 2020). Loss of vision in the central portion of the retina (macula), secondary to retinal degeneration. "Among them, four Hyper-LGs (CKB, PPP3CA, TGFB2, and SOCS2) overlapped with risk genes in the category of “macular degeneration” in the PHGKB." (PMID 32209064, 2020).
malaria (1 paper, 2018). Malaria is a serious and sometimes fatal disease caused by a parasite that commonly infects a certain type of mosquito which feeds on humans. "Four proteins (CA2, CKB, CKM, DAPK1) were only found to be associated with severe compared to mild malaria." (PMID 30442134, 2018).
medulloblastoma (1 paper, 2024). A malignant, invasive embryonal neoplasm arising from the cerebellum. "Despite the batch correction, certain proteins, like SERPINA1 in ALL patients and CKB in medulloblastoma patients, showed consistent trends across both the original and corrected data." (PMID 38350915, 2024). "For medulloblastoma, the most significant differences in rank order were observed in CKB, GFAP, and 26S proteasome non-ATPase regulatory subunit 14 (PSMD14)." (PMID 38350915, 2024).
melanoma (1 paper, 2022). A malignant, usually aggressive tumor composed of atypical, neoplastic melanocytes. "When comparing HEK293T cells to melanoma cells, we observed that among the significantly up-regulated proteins in HEK293T, there are proteins that might be tumor suppressor proteins, such as CKB that was low expressed in tumor cells." (PMID 36776379, 2022).
neuroblastoma (1 paper, 2025). Neuroblastoma (NB) is the most common solid, extracranial childhood tumor. "Notably, CKB and PCSK1N emerged as potential drivers of tumor progression, highlighting their promise as therapeutic targets in MYCN‐amplified neuroblastoma." (PMID 40600620, 2025).
Parkinson disease (1 paper, 2025). A progressive degenerative disorder of the central nervous system characterized by loss of dopamine producing neurons in the substantia nigra and the presence of Lewy bodies in the substantia nigra and locus coeruleus. "However, a study on Parkinson disease that utilized the NB cell line SY5Y suggested that CKB may be involved in energy metabolism of nerve cells." (PMID 40600620, 2025).
prostate adenocarcinoma (1 paper, 2021). "Interestingly, CKB is also downregulated in mouse prostate tumors from 2 independent studies on prostate-specific Pten knockout mice, a classic prostate adenocarcinoma mouse model." (PMID 34706306, 2021).
prostate tumors (1 paper, 2021). "Of note, patients whose prostate tumors expressing less CKB have faster biochemical relapse (rebound of serum PSA) (TCGA)." (PMID 34706306, 2021). "In summary, CKB downregulation, as observed in patient tumors, promotes prostate tumor progression and EMT." (PMID 34706306, 2021). "Interestingly, CKB is downregulated in prostate tumors from prostate-specific Pten conditional knockout models in at least 2 independent studies." (PMID 34706306, 2021).
systemic lupus erythematosus (1 paper, 2020). An autoimmune multi-organ disease typically associated with vasculopathy and autoantibody production. "In addition, CKB is also involved in the occurrence of some diseases, for example HCM, DCM, and systemic lupus erythematosus." (PMID 33281799, 2020).
uveitis (1 paper, 2014). An inflammatory process affecting a part of or the entire uvea. "A survey of retinal autoantigens associated with endogenous uveitis identified CKB, β-tubulin, β-actin, aspartate aminotransferase, and the voltage-dependent anion-selective channel protein as major contributors." (PMID 24955845, 2014).